UHRF1 (ubiquitin like with PHD and ring finger domains 1)
Diseases named in the same sentence as UHRF1 in open-access papers (continued):
Sharing a sentence is not in itself a finding about the gene and the disease.
osteosarcoma (6 papers, 2020 to 2024). A usually aggressive malignant bone-forming mesenchymal neoplasm, predominantly affecting adolescents and young adults. "This presents a new mechanistic insight into RB1 loss-associated poor prognosis and novel oncogenic roles of UHRF1 in the regulation of angiogenesis and exosome secretion, both critical for osteosarcoma metastasis." (PMID 36068209, 2022). "UHRF1 expression analysis using published RNA-Seq datasets from pretreatment biopsies from 88 osteosarcoma patients associate high UHRF1 expression with poorer overall survival." (PMID 36068209, 2022). "Given UHRF1 role in heterochromatin maintenance, we analyzed the effect of UHRF1 loss on DNA methylation, chromatin structure, and transcription to determine how UHRF1 serves as an oncogene in osteosarcoma." (PMID 36068209, 2022). "Uhrf1 loss drastically delayed tumor onset, decreased pulmonary metastasis, and increased the lifespan of developmental osteosarcoma mouse models carrying Rb1 mutation." (PMID 36068209, 2022). "UHRF1 expression analysis using pretreatment biopsies from 53 osteosarcoma patients associate low UHRF1 expression with increased rates of 5-year metastasis-free survival." (PMID 36068209, 2022). "This suggests that UHRF1 upregulation may contribute to tumor progression following RB1 loss in osteosarcoma." (PMID 36068209, 2022). "Further analyses on tumors arising from these developmental osteosarcoma models might provide insight on potential compensatory mechanisms of Uhrf1 loss which may be relevant for predicting mechanisms of resistance for future UHRF1-targeted therapeutics." (PMID 36068209, 2022). "Recent studies in osteosarcoma identified the overexpression of UHRF1 in several human osteosarcoma cell lines, indicating its significance in this cancer type." (PMID 39051184, 2024). "Both RB1-null and RB1-wild-type osteosarcoma cell lines appeared to equally benefit from targeting UHRF1." (PMID 36068209, 2022). "Our group is the first to model the critical role of UHRF1 in osteosarcomagenesis, with Uhrf1 KO resulting in a dramatic increase in overall survival and a decrease in metastases, particularly in Rb1-null osteosarcoma." (PMID 36068209, 2022). "Decreased genomic DNA methylation was detected in UHRF1 KO compared to VC in most osteosarcoma cells examined." (PMID 36068209, 2022). "Together, this indicates that UHRF1 overexpression alters the production and/or secretion of exosomes and/or its cargo which contribute, at least in part, to increased osteosarcoma cell migration." (PMID 36068209, 2022). "Here, we observed that UHRF1 is critical in osteosarcoma tumorigenesis, promoting proliferation, migration, angiogenesis, and metastasis." (PMID 36068209, 2022). "Novel osteosarcoma genetically engineered mouse models confirmed that knocking out Uhrf1 considerably decreased metastasis and reversed the poorer survival associated with Rb1 loss." (PMID 36068209, 2022). "Together, these results support the role of UHRF1 in the early stages of osteosarcoma metastasis, including tumor migration, invasion, and angiogenesis, and promotes tumor growth at secondary sites." (PMID 36068209, 2022). "UHRF1 mRNA in situ hybridization on an osteosarcoma tissue array confirmed a correlation between stage of malignancy and UHRF1 expression." (PMID 36068209, 2022). "UHRF1 KO osteosarcoma cells displayed a significant lower ability to induce endothelial cell sprouting compared to VC." (PMID 36068209, 2022). "Higher UHRF1 expression correlated with malignancy in osteosarcoma cell lines, clinical samples, and genetically engineered mouse models." (PMID 36068209, 2022). "PLAU transcript levels were significantly decreased in UHRF1 KO osteosarcoma cells and subcutaneous xenografts, with an average 2.2-fold decrease compared to VC cell-derived tumors (P = 0.038)." (PMID 36068209, 2022).
osteosarcoma (continued). "The clinical data led to examine UHRF1 mRNA and protein levels in 4 human osteosarcoma cell lines: 143B, SJSA-1, SaOS-2 (RB1-null cell line), and U-2 OS, and 5 patient-derived orthotopic xenografts (PDX1-5)." (PMID 36068209, 2022). "Here, we identified UHRF1 overexpression as directly correlated with increased osteosarcoma malignancy and metastatic disease." (PMID 36068209, 2022). "Targeting UHRF1 holds great potential in overcoming the highly metastatic characteristic of osteosarcoma, the main reason why the survival rate has remained stagnant in past decades." (PMID 36068209, 2022). "Moreover, the degree to which UHRF1 loss reverted the increased malignancy upon Rb1 loss suggests that the benefit of UHRF1 targeting could go beyond the scope of osteosarcoma by improving current treatment paradigms of other cancers harboring RB/E2F pathway inactivation." (PMID 36068209, 2022). "Doxycycline treatment for 24 h was able to restore UHRF1 protein expression back to levels comparable to wild-type and significantly increase migration in all osteosarcoma cell lines." (PMID 36068209, 2022). "To study the role of UHRF1 in osteosarcoma, we generated syngeneic UHRF1 CRISPR knockout clones (KO) and non-targeting vector controls (VC)." (PMID 36068209, 2022). "Inducible UHRF1 KO (iKO) and inducible VC (iVC) osteosarcoma cells were subcutaneously injected, and tumors allowed to establish for one week before inducing Cas9 expression via oral doxycycline delivery." (PMID 36068209, 2022). "This provides substantial support for targeting UHRF1 or its downstream effectors as novel therapeutic options to improve current treatment for osteosarcoma." (PMID 36068209, 2022). "This study supports targeting UHRF1 as a novel therapeutic strategy and provides alternative therapeutic interventions along the RB-UHRF1 axis for osteosarcoma treatment." (PMID 36068209, 2022). "Here, we determined the role and regulatory mechanisms of UHRF1 in rendering osteosarcoma cells more aggressive." (PMID 36068209, 2022). "UHRF1 was reported to promote cell invasion following exogenous UHRF1 overexpression in osteosarcoma." (PMID 36068209, 2022). "UHRF1 overexpression induced migration and invasion of normal MSCs and targeting UHRF1 drastically reduced migration and invasion of osteosarcoma cell lines." (PMID 36068209, 2022). "While conditioned media derived from osteosarcoma UHRF1 KO cells also increased cell migration compared to fresh media, VC cell migration was lower when exposed to UHRF1 KO conditioned media than autologous VC conditioned media (red bars)." (PMID 36068209, 2022). "We identified uPA as a critical factor in UHRF1-mediated migration, in line with a previous study describing the uPA/uPAR axis as a metastatic driver in osteosarcoma." (PMID 36068209, 2022). "Likewise, recent studies on osteosarcoma have found that when UHRF1 is overexpressed, osteosarcoma cells induce angiogenesis and become more invasive, ultimately becoming more metastatic." (PMID 39051184, 2024). "Finally, we evaluated UHRF1’s pro-oncogenic function in osteosarcoma tumorigenesis using developmental mouse models." (PMID 36068209, 2022). "Successful UHRF1 KO was achieved in all four osteosarcoma cell lines tested." (PMID 36068209, 2022). "Together, our data suggest UHRF1 is critical for osteosarcoma growth." (PMID 36068209, 2022). "Here, we evaluated whether the endogenously high UHRF1 protein levels present in osteosarcoma promote cell migration, invasion, angiogenesis, and metastasis." (PMID 36068209, 2022). "However, knocking down E2F1 alone was insufficient to decrease UHRF1 expression in osteosarcoma cells." (PMID 36068209, 2022). "The potential role of UHRF1 in migration and invasion through the control of exosome-mediated pathways was examined by testing the effect of conditioned media collected from VC and UHRF1 KO cell cultures on osteosarcoma cell migration." (PMID 36068209, 2022).
osteosarcoma (continued). "Thus, uPA is an important contributor of UHRF1-induced migration in osteosarcoma." (PMID 36068209, 2022). "Thus, UHRF1 loss decreases the secretion of pro-migratory factors to the extracellular matrix that can serve as an autologous signal to stimulate osteosarcoma cell migration but does not affect the ability of the cells to respond to these extracellular factors." (PMID 36068209, 2022). "Induction of a different UHRF1 gRNA in SJSA-1 resulted in similar tumor size reduction, as well as with other osteosarcoma cell lines." (PMID 36068209, 2022). "We tested compensation by other activator E2Fs and found that knocking down E2F1 alongside E2F3, but not E2F2, reduced UHRF1 expression in osteosarcoma." (PMID 36068209, 2022). "Thus, while the transcriptional regulation of UHRF1 is aberrant by means of RB/E2F pathway inactivation, RB1-wild-type osteosarcoma cells may preserve protein–protein interactions between RB and UHRF1." (PMID 36068209, 2022).
ovarian carcinoma (6 papers, 2015 to 2022). A malignant neoplasm originating from the surface ovarian epithelium. "The results highlighted that UHRF1 could act as a causative factor in ovarian cancer and as a suitable target for the development of anti-cancer therapies." (PMID 29899856, 2018). "Microarray analysis of epithelial ovarian cancer (EOC) along with matched healthy controls has recently identified UHRF1 as one of the key differentially upregulated genes during disease pathogenesis." (PMID 29899856, 2018). "Knockdown of UHRF1 in ovarian cancer cells inhibited their proliferation and induced apoptosis, suggesting UHRF1 as a general indicator of malignancy and an attractive therapeutic target for ovarian cancers." (PMID 28881702, 2017). "In a study including 80 samples from ovarian cancer tissues, significantly higher expression of UHRF1 was found at both transcriptomic and protein levels in tumors as compared with adjacent normal tissues." (PMID 28881702, 2017). "Recently, UHRF1 was found to be a new oncogenic factor in ovarian cancer as knockdown of UHRF1 inhibits ovarian cancer cell proliferation." (PMID 27780924, 2016).
renal cell carcinoma (6 papers, 2016 to 2025). "UHRF1 overexpression is associated with increased aggressiveness of tumors in renal cell carcinoma and acute myeloid leukemia cells." (PMID 40301374, 2025). "In the same context, renal cell carcinoma (RCC) tumors show high expression levels of UHRF1 compared to normal renal tissues, and this overexpression is associated with a decreased expression of the tumor suppressor gene TXNIP." (PMID 33922029, 2021). "In renal cell carcinoma (RCC), UHRF1 recruits histone deacetylase 1 (HDAC1) into the TXNIP promoter, reducing TXNIP expression and promoting the progression of RCC." (PMID 35450411, 2022).
medulloblastoma (5 papers, 2017 to 2024). A malignant, invasive embryonal neoplasm arising from the cerebellum. "The diagnostic and prognostic value of UHRF1 has also been evaluated in medulloblastoma, a common malignant brain tumor." (PMID 28881702, 2017). "Five genes were identified, including GLI1, which was reported to be regulated by the UHRF1/DNMT1 complex in medulloblastoma." (PMID 37380646, 2023). "A similar regulatory effect was recently observed in which UHRF1 was reported to be a direct target gene of miR-378 in medulloblastoma." (PMID 31442209, 2019). "Kaplan–Meier survival analysis showed that patients with high levels of UHRF1 had poor overall survival and progression free survival rate illustrating UHRF1 as a potential independent prognostic marker for medulloblastoma." (PMID 28881702, 2017). "Out of 168 formalin-fixed, paraffin-embedded medulloblastoma, high levels of UHRF1 were found in 108 cases while lower expression of UHRF1 was observed in the remaining 60 samples, whilst normal cerebellum tissue samples lacked UHRF1 staining." (PMID 28881702, 2017). "Moreover, in medulloblastoma, patients with high UHRF1 expression have significantly shorter overall survival and progression-free survival, reinforcing its prognostic value." (PMID 39051184, 2024). "On the other hand, UHRF1 downregulation can activate the expression of the tumor suppressor gene p16 and limit CDK4 to the cytoplasm in medulloblastoma cell lines, thereby impeding cell cycle progression." (PMID 39051184, 2024).
mesothelioma (5 papers, 2014 to 2024). A usually malignant and aggressive neoplasm of the mesothelium which is often associated with exposure to asbestos. "UHRF1 expression is significantly inhibited by treatment with repurposed chemotherapeutic drugs, such as mithramycin (a DNA-binding antitumor antibiotic produced by the bacterium Streptomyces plicatus), in MPM cells, suggesting UHRF1 as a druggable target in mesotheliomas." (PMID 37630248, 2023).
pulmonary fibrosis (5 papers, 2022 to 2025). Chronic progressive interstitial lung disorder characterized by the replacement of the lung tissue by connective tissue, leading to progressive dyspnea, respiratory failure, or right heart failure. "The upregulated pathways in UHRF1-null adipocytes included those linked with pulmonary fibrosis, hepatic fibrosis, ID1 signaling, pulmonary healing pathway, signaling by Rho Family GTPase, and Bex2 signaling." (PMID 38789534, 2024). "A recent study also reported knockdown of UHRF1 resulted in arrested lung fibroblasts proliferation and lung fibrosis." (PMID 40490444, 2025). "Another study reported that the methylation regulator Uhrf1 (Ubiquitin Like with PHD and Ring Finger Domains 1), upregulated in mouse models of pulmonary fibrosis, that promotes lung ferroptosis via epigenetic repression of GPX4 and FSP1 genes." (PMID 37664432, 2023). "A low level of UHRF1 or a high level of beclin 1, in turn, deactivated fibroblasts and blocked pulmonary fibrosis." (PMID 36166308, 2022). "In this study, we found that TGF-β1–mediated upregulation of UHRF1 repressed beclin 1 via methylated induction of its promoter, which resulted in fibroblast activation and lung fibrosis both in vitro and in vivo." (PMID 36166308, 2022). "Together, these data suggested that the administration of UHRF1 siRNA liposomes attenuates pulmonary fibrosis in multiple experimental mouse models." (PMID 36166308, 2022). "We found that intravenous administration of UHRF1 siRNA–loaded liposomes significantly protected mice against experimental pulmonary fibrosis." (PMID 36166308, 2022). "At last, we also preliminarily confirmed that the expression of UHRF1 was also significantly increased in activated fibroblasts during pulmonary fibrosis." (PMID 36566325, 2022). "In summary, our results suggest that liposomal-based UHRF1 siRNA is a potential therapy against pulmonary fibrosis." (PMID 36166308, 2022). "In the present study, we found that TGF-β1–mediated upregulation of UHRF1 repressed beclin 1 via methylated induction of its promoter, which finally resulted in fibroblast activation and lung fibrosis both in vitro and in vivo." (PMID 36166308, 2022). "Meanwhile, specific inhibition of UHRF1 highly arrests the ferroptosis formation and blocks the progression of pulmonary fibrosis in both of our research models." (PMID 36566325, 2022). "Intravenous administration of UHRF1 siRNA–loaded liposomes alleviated pulmonary fibrosis in multiple experimental mouse models." (PMID 36166308, 2022). "As an essential epigenetic regulator of DNA methylation, the involvement of ubiquitin-like containing PHD and RING finger domains 1 (UHRF1) in fibroblast activation remains largely undefined in pulmonary fibrosis." (PMID 36166308, 2022). "After the downregulation of UHRF1 in fibroblasts, the expression of beclin 1 was upregulated and then attenuated pulmonary fibrosis." (PMID 36166308, 2022). "Thus, intravenous administration of UHRF1 siRNA–loaded liposomes significantly protected mice against experimental pulmonary fibrosis." (PMID 36166308, 2022). "Therefore, we attempted to suppress silica- or bleomycin-induced (BLM-induced) mouse pulmonary fibrosis with UHRF1 siRNA–loaded cationic liposomes." (PMID 36166308, 2022). "Accordingly, our data suggested that UHRF1 might be a novel, potential therapeutic target in the pathogenesis of pulmonary fibrosis." (PMID 36166308, 2022). "Accordingly, our data suggest that UHRF1 might be a novel potential therapeutic target in the pathogenesis of pulmonary fibrosis." (PMID 36166308, 2022). "Collectively, these findings suggested that UHRF1 may play an essential role in regulating the procession of pulmonary fibrosis." (PMID 36166308, 2022). "Liposome UHRF1 siRNA could perform an ideal therapeutic efficiency of pulmonary fibrosis in vivo." (PMID 36566325, 2022).
pulmonary fibrosis (continued). "Therefore, our results suggest that target therapy against UHRF1 could be a feasible clinical approach in the treatment of pulmonary fibrosis." (PMID 36166308, 2022). "Specifically, injection of liposomes carrying UHRF1 siRNA in the tail vein reversed silica- and BLM-induced pulmonary fibrosis." (PMID 36166308, 2022). "Taken together, liposomal-based UHRF1 siRNA provided a practical, available, and safe therapeutic approach for silica- and BLM-induced pulmonary fibrosis." (PMID 36166308, 2022). "However, the function and expression of UHRF1 in fibroblasts have not been discussed in pulmonary fibrosis." (PMID 36166308, 2022). "This study first, to our knowledge, identified the involvement of Uhrf1 in mediating the ferroptosis of chemically injured AEC2s via de novo promoter-specific methylation of both GPX4 and FSP1 genes, which consequently accelerates the process of pulmonary fibrosis." (PMID 36566325, 2022).
thymoma (5 papers, 2019 to 2022). A neoplasm arising from the epithelial cells of the thymus. "Pseudogene RP11-424C20.2, which can predict a better prognosis in thymoma, acts as a ceRNA to enhance UHRF1 expression by sponging miR-378a-3p, consequently regulating IFN-γ-mediated CLTA-4 and PD-L1 activity in thymomas." (PMID 34496886, 2021). "Here, we reported that pseudogene RP11-424C20.2 and its parental gene UHRF1 were frequently up-regulated and positively correlated in liver hepatocellular carcinoma (LIHC) and thymoma (THYM), but associated with distinct clinical outcomes." (PMID 31442209, 2019). "Therefore, RP11-424C20.2 expression can influence the prognosis of patients with thymoma by regulating the expression of UHRF1 via miR-378a-3p sponging." (PMID 35529877, 2022). "RP11-424C20.2 and its parental gene UHRF1 have elevated expression levels in patients’ liver hepatocellular carcinoma (LIHC) and thymoma (THYM)." (PMID 34947885, 2021). "In this study, we found that RP11-424C20.2 expression was strongly correlated with UHRF1 and RP11-424C20.2/UHRF1 axis functioned as a disparate role in LIHC and thymoma (THYM) through regulating immune infiltration." (PMID 31442209, 2019).
acute myeloid leukemia (4 papers, 2023 to 2025). Acute myeloid leukemia (AML) is a group of neoplasms arising from precursor cells committed to the myeloid cell-line differentiation. "UHRF1 is markedly overexpressed in acute myeloid leukemia (AML) cells, with elevated levels strongly correlating with poor prognosis." (PMID 40429796, 2025).